PNPT1 (polyribonucleotide nucleotidyltransferase 1)
Description:
RNA-binding protein implicated in numerous RNA metabolic processes. Catalyzes the phosphorolysis of single-stranded polyribonucleotides processively in the 3'-to-5' direction. Mitochondrial intermembrane factor with RNA-processing exoribonulease activity. Component of the mitochondrial degradosome (mtEXO) complex, that degrades 3' overhang double-stranded RNA with a 3'-to-5' directionality in an ATP-dependent manner. Involved in the degradation of non-coding mitochondrial transcripts (MT-ncRNA) and tRNA-like molecules. Required for correct processing and polyadenylation of mitochondrial mRNAs. Plays a role as a cytoplasmic RNA import factor that mediates the translocation of small RNA components, like the 5S RNA, the RNA subunit of ribonuclease P and the mitochondrial RNA-processing (MRP) RNA, into the mitochondrial matrix. Plays a role in mitochondrial morphogenesis and respiration; regulates the expression of the electron transport chain (ETC) components at the mRNA and protein levels. In the cytoplasm, shows a 3'-to-5' exoribonuclease mediating mRNA degradation activity; degrades c-myc mRNA upon treatment with IFNB1/IFN-beta, resulting in a growth arrest in melanoma cells. Regulates the stability of specific mature miRNAs in melanoma cells; specifically and selectively degrades miR-221, preferentially. Also plays a role in RNA cell surveillance by cleaning up oxidized RNAs. Binds to the RNA subunit of ribonuclease P, MRP RNA and miR-221 microRNA.
Synonyms: PNPASE; OLD35; old-35; COXPD13; DFNB70; SCA25
Tractability: Antibody: UniProt places it where antibodies can reach, with high confidence. PROTAC: ubiquitination databases record sites on it; its protein half-life has been measured.
Gene: Protein-coding gene on chromosome 2 (55,634,061 to 55,693,863, reverse strand). Ensembl gene ENSG00000138035.
Subcellular location: Cytoplasm; Mitochondrion matrix; Mitochondrion intermembrane space
Subcellular location (Human Protein Atlas): Mitochondria; Cytosol
Pathways (Reactome):
Metabolism of RNA: Mitochondrial RNA degradation
Gene Ontology:
Molecular function: 3'-5'-RNA exonuclease activity; identical protein binding; miRNA binding; poly(G) binding; poly(U) RNA binding; polyribonucleotide nucleotidyltransferase activity; protein binding; RNA binding; nucleic acid binding
Biological process: cellular response to interferon-beta; cellular response to oxidative stress; mitochondrial mRNA catabolic process; mitochondrial mRNA polyadenylation; mitochondrial RNA 3'-end processing; mitochondrial RNA 5'-end processing; mitochondrial RNA catabolic process; mRNA catabolic process; nuclear polyadenylation-dependent mRNA catabolic process; positive regulation of miRNA catabolic process; positive regulation of mitochondrial RNA catabolic process; positive regulation of mRNA catabolic process; protein homooligomerization; protein homotrimerization; regulation of cellular senescence; RNA catabolic process; RNA import into mitochondrion; rRNA import into mitochondrion; mitochondrion organization; regulation of cellular respiration; liver regeneration; response to cAMP; response to growth hormone; RNA processing
Cellular component: cytoplasm; cytosol; mitochondrial degradosome; mitochondrial intermembrane space; mitochondrial matrix; mitochondrion; endoplasmic reticulum membrane; exoribonuclease complex; ribosome
Genetic constraint (gnomAD): Loss-of-function variants: 39 observed, 79.6 expected, observed/expected ratio (o/e) 0.49, 90% interval 0.38 to 0.64. The upper end of that interval is the gene's LOEUF score, 0.64, which puts it in group 2 of 6, group 1 being the genes least tolerant of losing a copy. Missense variants: 704 observed, 725.24 expected, observed/expected ratio (o/e) 0.97, 90% interval 0.91 to 1.03. Synonymous variants: 280 observed, 255.49 expected, observed/expected ratio (o/e) 1.1, 90% interval 0.99 to 1.21.
Gene-disease validity (ClinGen):
ClinGen rates the evidence that PNPT1 causes each of these diseases.
Leigh syndrome (autosomal recessive): Moderate. A progressive neurological disease defined by specific neuropathological features associating brainstem and basal ganglia lesions.
Homologues: Orthologues: chimpanzee PNPT1 (98% identical), macaque PNPT1 (98% identical), rabbit PNPT1 (94% identical), dog PNPT1 (94% identical), pig PNPT1 (93% identical), guinea pig PNPT1 (92% identical), rat Pnpt1 (92% identical), mouse Pnpt1 (91% identical), tropical clawed frog pnpt1 (77% identical), Drosophila melanogaster PNPase (55% identical), Caenorhabditis elegans BE0003N10.1 (39% identical).